MIR7848 (microRNA 7848)
Synonyms: hsa-mir-7848
Gene: MicroRNA gene on chromosome 8 (133,046,481 to 133,046,581, reverse strand). Ensembl gene ENSG00000276961.
Homologues: Orthologues: chimpanzee MIR7848 (100% identical).